CD36 (CD36 molecule (CD36 blood group))
Diseases named in the same sentence as CD36 in open-access papers (continued):
Sharing a sentence is not in itself a finding about the gene and the disease.
osteosarcoma (3 papers, 2024 to 2025). A usually aggressive malignant bone-forming mesenchymal neoplasm, predominantly affecting adolescents and young adults. "CD36, known for its involvement in fatty acid metabolism and angiogenesis, has been implicated in inflammasome activation, which is pivotal in osteosarcoma's inflammatory and metastatic processes." (PMID 38742843, 2024). "Recent studies indicate that CD36 plays a significant role in osteosarcoma, acting not only as a key biomarker for prognosis but also as a potential therapeutic target, thereby providing new strategies for personalized treatment of the disease." (PMID 40075313, 2025). "Validation of gene expression through public databases and RT-qPCR results showed significant upregulation of EPYC and PANX3 in osteosarcoma samples, while CD36, CLDN11, and STOM were significantly downregulated." (PMID 40075313, 2025). "However, the literature presents conflicting views on CD36’s role; while downregulation of CD36 mRNA has been reported to reduce osteosarcoma cell proliferation, further investigation is needed to clarify its function in osteosarcoma." (PMID 40075313, 2025). "The five biomarkers (CD36, CLDN11, EPYC, PANX3, and STOM) were screened to construct an AAMRGs risk model with prognostic value, providing a new reference for the prognosis and treatment of osteosarcoma." (PMID 40075313, 2025). "ZCCHC12 can promote the progression of osteosarcoma through the PI3K/AKT pathway, and ZCCHC12+ tumor cells in papillary thyroid cancer interact with CD36+ pro-inflammatory macrophages to promote tumor progression and recurrence." (PMID 41438761, 2025). "The differential analysis showed that in the osteosarcoma group, the expression of EPYC and PANX3 was obviously elevated, whereas the expression of CD36, CLDN11 and STOM was markedly decreased." (PMID 40075313, 2025). "In vitro experiments validated CD36 and MYD88's roles in promoting osteosarcoma cell proliferation, invasion and migration, emphasising their therapeutic potential." (PMID 38742843, 2024). "In addition, CD36, CLDN11 and STOM were found to have lower expression between osteosarcoma tissue samples compared to para-carcinoma tissue." (PMID 40075313, 2025). "The roles of PANX3 and CD36 are well established; however, the specific functions of EPYC, CLDN11, and STOM in osteosarcoma remain unclear." (PMID 40075313, 2025). "In order to develop a risk model with the optimal prognostic predictive capacity of these DE-AAMRGs in osteosarcoma patients, we performed univariate Cox analysis and utilized the LASSO method to select a panel of five biomarkers (CD36, CLDN11, EPYC, PANX3, and STOM)." (PMID 40075313, 2025). "The rationale for focusing on CD36 and MYD88 as therapeutic targets is underpinned by studies that demonstrate their involvement in tumorigenic processes and their specific impact on inflammasome regulation, which can significantly influence the progression and aggression of osteosarcoma." (PMID 38742843, 2024).
periodontal disease (3 papers, 2015 to 2024). "Murine formylpeptide receptor (mFPR2) and Class B scavenger receptor CD36 were not significantly affected by the periodontal disease microbiome." (PMID 37316834, 2023).
pneumonia (3 papers, 2021 to 2024). An acute, acute and chronic, or chronic inflammation focally or diffusely affecting the lung parenchyma, caused by an infection in one or both of the lungs (by bacteria, viruses, fungi, or mycoplasma.). "In influenza virus-mediated pneumonia, the expression of CD36 was downregulated and since the host is more susceptible to infection when CD36 is absent, CD36-mediated phagocytosis is required to eliminate germs." (PMID 38881887, 2024). "CD36 inhibition is a promising therapeutic approach for improving pneumonia outcomes in aging population." (PMID 37566016, 2023).
pulmonary tuberculosis (3 papers, 2017 to 2025). A bacterial infection that affects the lungs and is caused by Mycobacterium tuberculosis. "In addition, CD36 variants have been studied in pulmonary TB among the Chinese Han population, but these investigations focused on different CD36 polymorphisms (rs1194182, rs10499859) and MARCO variants." (PMID 41410218, 2025). "Single nucleotide polymorphisms (SNP) in CD36 indicated the risk of pulmonary tuberculosis is decreased in SNPs due to the reduced ability of CD36 to recognize the M. tuberculosis pattern recognition molecules indicated CD36 as important receptors in response to PTB." (PMID 38881887, 2024). "In summary, our findings demonstrated that genetic variations in the scavenger receptors, MARCO and CD36, might be associated with susceptibility/resistance to pulmonary tuberculosis in a Chinese Han population." (PMID 28693442, 2017). "Whether MARCO and CD36 are associated with extra-pulmonary tuberculosis, such as TBM, or intestinal, bone and urinary tuberculosis, needs further investigation." (PMID 28693442, 2017).
sarcoma (3 papers, 2016 to 2021). A usually aggressive malignant neoplasm of the soft tissue or bone. "Elevated CD36 expression is linked with enhanced aggressiveness in carcinomas and sarcomas." (PMID 34314388, 2021). "The relative binding affinity measurements (EC50 values) of the peptide analogues correlated with CD36-dependent phosphorylation of sarcoma, src-kinases (Lyn/Fyn) in CD36 expressing J774 macrophages." (PMID 32717955, 2020).
sickle cell disease (3 papers, 2022 to 2025). Sickle cell anemias are chronic hemolytic diseases that may induce three types of acute accidents: severe anemia, severe bacterial infections, and ischemic vasoocclusive accidents (VOA) caused by sickle-shaped red blood cells obstructing small blood vessels and capillaries. "HU is also known for modulating the expression of several adhesion molecules on RBCs, but evidence shows that it contributes by reducing the expression of molecules such as α4β1, CD36, VLA-4, and ICAM-4 of erythroid cells from sickle cell disease patients." (PMID 40507944, 2025).
squamous cell carcinoma (3 papers, 2019 to 2025). A carcinoma arising from squamous epithelial cells. "In human colorectal and squamous cell carcinoma cells, lipid uptake via cluster determinant 36 (CD36) is required for acid-induced lipid droplet formation." (PMID 39284708, 2024). "Squamous cell carcinoma is linked to the expression of MARCKS, CD36, DAB2, ENPEP, and TIMP1." (PMID 40565366, 2025).
acute liver failure (2 papers, 2021 to 2025). Rapid deterioration of liver function causing encephalopathy and coagulopathy. "CD36 may therefore serve as a target for therapeutic intervention in acute liver failure." (PMID 34092215, 2021).
age (2 papers, 2014 to 2018). A temporal measurement of the time period elapsed since an identifiable point in the life cycle of an organism. "Thus, our data indicate that enhanced CD36-mediated hepatic fat uptake may contribute to an accelerated progression of age-related NAFLD in both mice and humans." (PMID 24751397, 2014).
alcoholic fatty liver disease (2 papers, 2022 to 2023). Lipid infiltration of the hepatic parenchymal cells that is due to alcohol abuse. "However, similar to HCC, an increased expression of the fatty acid translocase CD36 seems an important trait involved in the development of alcoholic fatty liver disease." (PMID 37108625, 2023).
alcoholic hepatitis (2 papers, 2019 to 2020). Acute hepatitis resulting from ingestion of alcohol. "The idea here is that activated macrophages internalize increased amounts of oxLDLs via CD36 and SRA1 and that contributes to the pathophysiology of severe alcoholic hepatitis." (PMID 32848838, 2020). "Patients manifesting severe alcoholic hepatitis, inflammation and oxidative stress symptoms had a correlation with a decrease of circulating paroxanase/arylesterase 1 (PON1) in the blood and stimulated alternatively activated (M2) macrophages through activation of CD36." (PMID 32848838, 2020). "To investigate the clinical relevance of our findings, we examined the protein levels of Nogo-B, CD36, CEBPβ, and p-YAP by western blot analysis in 16 pairs of human NAFLD-associated HCCs without either viral or alcoholic hepatitis, and 12 pairs of HBV-positive HCC patients." (PMID 31358770, 2019).
Allergy (2 papers, 2021 to 2023). An allergy is an immune response or reaction to substances that are usually not harmful. "Furthermore, the fatty acid translocase CD36 is 20-fold stronger expressed in CD11b+CD11c+ MDSCs than in CD11b+CD11c− MDSCs and serves in association with the platelet-activating factor receptor as an important mediator of Th2-mediated house dust mite allergy development." (PMID 34721430, 2021). "Similar observations could be made for other molecules such as CD36, demonstrated to be involved in HDM induced allergy development." (PMID 37296179, 2023).
aneurysm (2 papers, 2021 to 2023). Bulging or ballooning in an area of an artery secondary to arterial wall weakening. "Our results showed that GSH and CD36 have poor discrimination between IA patients and HCs when clinical characteristics were combined with aneurysm parameters." (PMID 38196515, 2023). "The logistic regression model showed a normal distribution, and the GSH and CD36 values had a good linear relationship with the response variables (clinical data and aneurysm parameters)." (PMID 38196515, 2023). "Also, the expression of CD36 significantly correlated with the height of the aneurysm in the internal carotid artery IA patients (P = 0.0490, r = −0.6485)." (PMID 38196515, 2023). "To evaluate the relationship between CD36, GSH, and clinical parameters of IA patients, we analyzed the correlation among the expression levels of CD36, GSH, IA clinical data, and aneurysm parameters." (PMID 38196515, 2023). "Third, our correlation analysis indicated that the expression levels of CD36 and GSH did not correlate with the aneurysm parameters, which implies that they might not participate in the changes in the aneurysm morphology." (PMID 38196515, 2023). "We proposed that CD36 and GSH might be involved in the progress of IA rupture but did not affect the aneurysm morphology." (PMID 38196515, 2023).
Arrhythmia (2 papers, 2022). Any cardiac rhythm other than the normal sinus rhythm. "CD36 deficiency in rodents was reported to associate with intolerance to prolonged fasting with increases in arrhythmias and sudden death." (PMID 36061565, 2022). "Higher arrhythmia burden and mortality in Cd36−/− and Mertk−/− mice, viewed together with reduced mitochondrial integrity and accelerated cardiomyocyte death in the absence of macrophages, indicated that receptor-mediated phagocytosis protects against lethal electrical storm." (PMID 36034743, 2022).
Cachexia (2 papers, 2021 to 2023). Severe weight loss, wasting of muscle, loss of appetite, and general debility related to a chronic disease. "Consistently, the loss of epididymal adipose tissues in cachexia mice was accompanied by upregulated expressions of fatty acid translocase CD36 and Acyl-coenzyme A thioesterase 1 (Acot1) in the CAC gastrocnemius, which facilitated mobilization and oxidation of adipose tissues." (PMID 34229732, 2021). "HF-induced cachexia elevated the mRNA expression levels of Cd36, Fatp-1 and Cpt-1 (P < 0.01)." (PMID 36670439, 2023).
cholangiocarcinoma (2 papers, 2020 to 2025). A carcinoma that arises from the intrahepatic biliary tree (intrahepatic cholangiocarcinoma) or from the junction, or adjacent to the junction, of the right and left hepatic ducts (hilar cholangiocarcinoma). "However, CD36, GGCX, UBASH3B, DBN1, PTTG1, CCNA2, and SPATS2 are found in other tumors to regulate tumor progression, which may also regulate cholangiocarcinoma progression and affect the recurrence of CCA." (PMID 32071556, 2020).
Cholestatic liver disease (2 papers, 2022 to 2025). "CD36 has been identified as a regulator of the hepatic circadian clock and metabolic processes; however, the specific mechanisms by which CD36 links circadian rhythms to cholestatic liver disease remain unclear." (PMID 42004228, 2025). "Consistent with increased oxidation of cholesterol we find increased CD36 expression in the livers of mice fed the HFHC diet for 24 weeks, given the Lieber-DeCarli diet and the Mdr2−/− model of cholestatic liver disease." (PMID 36338478, 2022).
chronic hepatitis B (2 papers, 2024 to 2025). "Interestingly, a study involving patients with chronic hepatitis B found increased expression of CD36 in peripheral blood monocytes when patients were anxious." (PMID 39774047, 2025).
colorectal tumor (2 papers, 2019 to 2025). "Consistent with public data, mRNA and protein levels of CD36 by quantitative real-time polymerase chain reaction (qRT-PCR) and western blot analysis were similarly decreased in colorectal tumors as compared with their paired normal tissues." (PMID 31484922, 2019). "Our data suggested that AAV-mediated CD36 knockdown promoted more and larger colorectal tumor formation in AOM/DSS-induced CRC." (PMID 31484922, 2019). "Collectively, these results strongly argued for CD36 as a colorectal tumor suppressor whose expression may serve as an early biomarker for assessing malignant transformation risk and an intervention target of colorectal neoplasia." (PMID 31484922, 2019).
diabetic retinopathy (2 papers, 2020 to 2022). "Therefore, COX-2 may play an important role in ischemic proliferative retinal diseases such as diabetic retinopathy by inhibiting CD36." (PMID 36611964, 2022).
ductal carcinoma in situ (2 papers, 2023 to 2025). "CD36 loss and CD31 gain in the capillary vasculature were more commonly observed surrounding ductal carcinoma in situ (DCIS) associated with subsequent IBC." (PMID 37816052, 2023). "When evaluated in perilesional capillaries surrounding ductal carcinoma in situ, a nonobligate IBC precursor, CD36 loss was more commonly observed in lesions associated with subsequent IBC." (PMID 37816052, 2023).
emphysema (2 papers, 2021 to 2024). "In chronic obstructive pulmonary disease (COPD), CD36 has been shown to play a role in the progression of emphysema, particularly in the context of elastase‐induced disease advancement." (PMID 39552437, 2024).
gastric adenocarcinoma (2 papers, 2022 to 2025). "The expression levels of CD36 mRNA were notably decreased in gastric adenocarcinoma when compared to adjacent normal gastric tissues (P value < 0.05)." (PMID 40061897, 2025). "RT-qPCR results indicated that the mRNA expression levels of four hypoxic endoplasmic reticulum stress-related differential genes—NOX4, ANGPT2, CD36, and TLR2—were correlated with our established prognostic risk model in both gastric adenocarcinoma and adjacent normal tissues." (PMID 40061897, 2025). "By contrast, in gastric adenocarcinoma, elevated CD36 expression and increased lipid content are important to the survival of CD8+ Trm cells, indicating the positive role of CD36 in antitumor responses." (PMID 39872079, 2022).
gastric tumor (2 papers, 2019 to 2020). "In order to evaluate whether FAs could promote metastasis of a gastric tumor and whether this process was mediated by CD36 in vivo, a peritoneal dissemination assay was performed in nude mice." (PMID 30717785, 2019).
gastritis (2 papers, 2021 to 2024). Inflammation of the stomach. "In terms of gastrointestinal disorders, loss of CD36 in endothelial cells impairs stomach function and mucosal renewal after injury, associated with the increasing risk of ulcer, gastritis, and gastrointestinal hemorrhage." (PMID 39524404, 2024). "The association of low CD36 mRNA with gastric ulcer, gastritis, duodenitis, and gastrointestinal hemorrhage in the BioVu database suggests CD36 is critical for human gastric homeostasis." (PMID 34728772, 2021). "Relevance to humans is explored in the Vanderbilt BioVu using PrediXcan that links genetically-determined gene expression to clinical phenotypes, which associates low CD36 mRNA with gastritis, gastric ulcer, and gastro-intestinal hemorrhage." (PMID 34728772, 2021). "The clinical impact of our work is highlighted by the finding that the defect of gastric recovery in low CD36 expression might be one underlying mechanism in the etiology of ulcer, gastritis, and gastrointestinal hemorrhage." (PMID 34728772, 2021). "We identified significant associations between genetically reduced CD36 expression and increased incidence of gastric ulcer, gastritis, duodenitis, and nonspecific hemorrhage of the gastrointestinal tract." (PMID 34728772, 2021).
Gastrointestinal hemorrhage (2 papers, 2021 to 2024). Hemorrhage affecting the gastrointestinal tract. "This interpretation is further buttressed by the identification of a previously unstudied CD36 SNP that strongly associates with death from gastrointestinal hemorrhage in the UK Biobank, providing additional support for relevance of the CD36 gene to gastrointestinal pathology." (PMID 34728772, 2021).
glomerulosclerosis (2 papers, 2005 to 2025). A hardening of the kidney glomerulus caused by scarring of the blood vessels. "In contrast, in diabetic mice with albuminuria, mesangial expansion, and glomerulosclerosis, absence of CD36 expression was associated with normal appearance of the tubular epithelium and interstitial space." (PMID 15737001, 2005).
hemorrhage (2 papers, 2024 to 2025). Loss of blood from the vascular compartment to the exterior or into nonvascular body space as a result of rupture or severance of the blood vessels. "The lack of circadian dependency regarding the inflammatory response and functional outcome after hemorrhage was further demonstrated in CD36−/− mice in vivo to support the previous notion that circadian rhythmicity determines protective effects related to CD36 and CO." (PMID 38338958, 2024).
HIV-1 infection (2 papers, 2007 to 2010). The type species of lentivirus and the etiologic agent of acquired immunodeficiency syndrome (AIDS). "Although the association between HIV-1 infection and the increased expression of CD36 has been more recently confirmed in a large cohort of HIV-1 infected patients, a careful statistical analysis cast doubts on the real impact of PIs treatment in the pathogenesis of this abnormality." (PMID 20548796, 2010). "Furthermore, expression of several other molecules is increased on monocytes after HIV-1 infection, e.g. CD23, CD36, CD14, CD126, HLA-G, and sialoadhesin (and this study)." (PMID 17330143, 2007).
hyperhomocysteinemia (2 papers, 2016 to 2025). A serious metabolic condition caused by mutations in the MTHFR gene, medications, or nutritional deficiency. "In addition, hyperhomocysteinemia (hyperHcy) can also increase the expression of CD36, the scavenger receptor of oxidized-LDL (ox-LDL), in macrophages, resulting in the formation of foam cells." (PMID 40531765, 2025).
hyperthyroidism (2 papers, 2022 to 2023). Overactivity of the thyroid gland resulting in overproduction of thyroid hormone and increased metabolic rate. "Furthermore, we also revealed marked upregulation of Cd36 following the induction of hyperthyroidism." (PMID 35883786, 2022).
infarction (2 papers, 2022). A localised pathological necrosis of tissue resulting from obstruction of the blood supply usually by a thrombus, an embolus, or vascular torsion. "Although FAT/CD36 overexpressed heart reduces infarction size following infarction." (PMID 34529222, 2022).
invasive breast carcinoma (2 papers, 2018 to 2023). A carcinoma that infiltrates the breast parenchyma. "In a previous study of tissue microenvironments, our laboratory identified CD36 repression as a characteristic of the invasive breast cancer (IBC)-associated stroma and the stroma of tissue at high risk for future cancers." (PMID 37816052, 2023). "Although robustly expressed in the disease-free (DF) breast stroma, CD36 is consistently absent from the stroma surrounding invasive breast cancers (IBCs)." (PMID 37816052, 2023).